SAA1 (serum amyloid A1)
Diseases named in the same sentence as SAA1 in open-access papers (continued):
Sharing a sentence is not in itself a finding about the gene and the disease.
lymph node metastasis (4 papers, 2019 to 2026). "Clinical sample validation confirmed that SAA1 expression was associated with increased lymph node metastasis." (PMID 31390756, 2019). "Multiple studies have shown that high expression of SAA1 is associated with the development of CRC, lymph node metastasis, and poor prognosis." (PMID 41459112, 2026).
osteoporosis (4 papers, 2013 to 2019). A condition of reduced bone mass, with decreased cortical thickness and a decrease in the number and size of the trabeculae of cancellous bone (but normal chemical composition), resulting in increased fracture incidence. "We found that SAA1 rs10832915 polymorphisms conferred susceptibility to osteoporosis under codominant and allelic models." (PMID 30737305, 2019). "The CC genotype and C allele were associated with TC, LDL, HDL, T-score, Z-score and lower SAA1 levels in osteoporosis patients." (PMID 30737305, 2019). "They found that the CC genotype of the rs12218 polymorphism expressed more SAA1 and increased the risk of osteoporosis compared with the TT genotype." (PMID 30737305, 2019). "Although two studies have reported an association between the SAA1 rs12218 polymorphism and the risk of osteoporosis, their findings conflicted." (PMID 30737305, 2019). "The gene for SAA1 was considered as a candidate for osteoporosis because it is the gene encoding one important inflammatory factor; SAA." (PMID 26648999, 2015). "In this study, our aim was study the relationship between SAA1 gene polymorphism (rs12218) and lipid profile and osteoporosis." (PMID 26648999, 2015). "In this study, we aimed to study the relationship between SAA1 gene polymorphism (rs12218) and lipid profile and osteoporosis." (PMID 26648999, 2015). "The present results indicate that both osteoporosis and lipids levels are associated with the TT genotype of rs12218 in the human SAA1 gene." (PMID 23522429, 2013). "Therefore, this case–control study which enrolled 300 osteoporosis patients and 350 controls was conducted to evaluate the role of SAA1 gene polymorphisms in the risk of osteoporosis in a Chinese population." (PMID 30737305, 2019). "In conclusion, the SAA1 rs10832915 polymorphism may be a genetic contributor to the risk of osteoporosis in the Chinese Han population." (PMID 30737305, 2019). "The SAA1 gene rs10832915 polymorphism increased the risk of osteoporosis in our Chinese population." (PMID 30737305, 2019). "SAA1 gene polymorphisms may alter the gene expression and function and modulate osteoporosis susceptibility." (PMID 30737305, 2019). "We hypothesized that this polymorphism conferred susceptibility to osteoporosis by regulating the SAA1 level." (PMID 30737305, 2019). "Therefore, we performed this case–control study to evaluate the association between SAA1 gene polymorphisms and the risk of osteoporosis." (PMID 30737305, 2019). "In conclusion, the SAA1 gene polymorphism was associated with osteoporosis in Chinese population." (PMID 23522429, 2013). "This study assessed the correlation between SAA1 gene rs12218 polymorphism and HDL-C lelvels and osteoporosis in a population of Chinese women." (PMID 23522429, 2013). "Also, TT genotype and T allel was found to be associated with plasma total cholesterol, TG, LDLc, HDLc, Tscore, Zscore and SAA1 level in osteoporosis group (P=0.000, P=0.05, and P=0.000, P=0.000, P=0.01, P=0.02, P=0.000 respectively)." (PMID 26648999, 2015). "Correlations between SAA1 gene rs12218 polymorphism and osteoporosis and HDL-C level were investigated through the identification of SAA1 gene rs12218 polymorphism genotypes using the polymerase chain reaction-restriction fragment length polymorphism (PCR-RFLP)." (PMID 23522429, 2013). "However, there are few reports on the role of SAA1 in the etiology of osteoporosis." (PMID 30737305, 2019). "In the present study, we aim to study the relationship between SAA1 gene polymorphsim (rs12218) and HDL-C level and osteoporosis." (PMID 23522429, 2013).
renal cell carcinoma (4 papers, 2019 to 2023). "LINC00160 mediates sunitinib resistance in renal cell carcinoma via SAA1 that is implicated in STAT3 activation and compound transportation, which offers an opportunity for targeted intervention and molecular therapies in the future." (PMID 32921632, 2020). "SAA1 has been reported to function as a biomarker for advanced renal cell carcinoma." (PMID 32921632, 2020). "For example, as a member of the serum amyloid A family of apolipoproteins, SAA1 can increase the invasive capacity of tumor cells in RCC by inducing MMP-9 expression, which make it serve as a biomarker for the diagnosis and prognosis of advanced and metastatic renal cell carcinoma." (PMID 34712244, 2021).
steatosis (4 papers, 2021 to 2026). Increased lipid within the cytoplasm of cells. "Expression of the pro-inflammatory cytokine, SAA1, a factor associated with radiation-induced acute inflammatory response, was increased at 17 days post-irradiation, concurrent with steatosis." (PMID 40440310, 2025). "Preclinical data suggest that genetic deletion or hepatic knockdown of Saa1/2 enhances energy expenditure and attenuates high-fat diet (HFD)-induced steatosis, metabolic dysfunction, and hepatic inflammation." (PMID 41313351, 2026). "Four genes had lower expression in steatosis (ABCA1, MTR, MTHFR, and PLG) and five genes had higher expression (SEPHS2, DIO1, HBB, SAA1, and SAA2) in the “selenoprotein micronutrient network” pathway." (PMID 34869521, 2021).
tuberculosis (4 papers, 2017 to 2025). A chronic, recurrent infection caused by the bacterium Mycobacterium tuberculosis. "The capacity of macrophages is modulated by a number of factors including SAA1, which is highly upregulated in response to inflammation, as well as, during tuberculosis." (PMID 37781389, 2023). "Considering our research and literature data, it can be assumed that the observed, elevated SAA-1 level in tuberculosis patients modulates both, the host immune response and the functional response of mycobacteria during infection." (PMID 37781389, 2023). "Of identified core proteins, complement factor H formed a diagnostic classifier that distinguished latent Mtb infection from healthy controls with good performance, and we also identified C4B, MBL2, SAA1, and matrix Gla protein as potential proteomic signatures of active tuberculosis." (PMID 40736242, 2025). "Saa3 expression was upregulated in the bone of both M. avium- and M. tuberculosis-infected mice and SAA1 and 2 proteins (that share a high homology with murine SAA3 protein) were increased in the serum of patients with active tuberculosis." (PMID 37153579, 2023).
astrocytoma (3 papers, 2018 to 2021). "We used data from GlioVis to detect the hub gene expression level between GBM and LGG including astrocytoma, oligodendroglioma, and oligoastrocytoma, the expression level of SAA1 and TIMP1 significantly increased in GBM." (PMID 30867991, 2019). "The gene expression of SAA1 in patients with GBM (214 cases) was at least fourfold higher than that in patients with oligodendrogliomas (66 cases) (P = 0.0062), patients with astrocytomas (145 cases) (P < 0.0001), and normal patients (21 cases) (P = 0.05)." (PMID 29603594, 2018).
Autoimmunity (3 papers, 2023 to 2025). The occurrence of an immune reaction against the organism's own cells or tissues. "This links neutrophil-driven Saa3/SAA1 signaling to human CNS autoimmunity and points to therapeutic and diagnostic potential." (PMID 41333423, 2025). "In addition, ASR1 together with its interacting TF 1 (AITF1) can directly activate the SAA1 expression through binding to the GT-boxes in SAA1 promoter and further modulate the plant disease resistance and autoimmunity." (PMID 38877454, 2024).
clear cell renal cell carcinoma (3 papers, 2023 to 2024). "Recent studies have suggested that SAA1 is involved in the immune microenvironment of clear cell renal cell carcinoma (ccRCC)." (PMID 39744064, 2024).
colorectal cancer (3 papers, 2022 to 2024). A primary or metastatic malignant neoplasm that affects the colon or rectum. "In addition, tumor‐associated macrophages promote aggressive behavior by colorectal cancer cells through upregulation of SAA1 via IL‐1β signaling." (PMID 37081987, 2023). "Tumor-associated macrophages promote cancer cell migration and invasion by inducing serum amyloid A1 (SAA1) at the early colorectal cancer (CRC) invasion front." (PMID 39100676, 2024). "For example, SAA1 produced by colorectal cancer cells recruits neutrophils to the invasive front of colorectal cancer, and stimulates neutrophils to produce CXCL8 and MMP-9, which contribute to tumor progression." (PMID 37081987, 2023). "In a colorectal cancer (CRC) model, macrophage-derived IL-1β was shown to elicit the production of serum amyloid A1 (SAA1) by tumor cells, which in a feed-forward manner induced macrophages to upregulate metalloproteinase-9 secretion allowing cancer migration and establishment of metastasis." (PMID 35517498, 2022).
endometrial cancer (3 papers, 2022 to 2025). Primary or metastatic malignant neoplasm involving the endometrium (mucous membrane that lines the endometrial cavity). "To further confirm the correlation between LCN2 and SAA1/2 expression and endometrium cancer, we analyzed The Cancer Genome Atlas (TCGA) cohorts and observed significantly upregulated LCN2 and SAA1/2 expression in EEC cases compared with normal samples." (PMID 36273006, 2022).
esophageal squamous cell carcinoma (3 papers, 2022 to 2024). Esophageal squamous cell carcinoma (ESCC) is a type of esophageal carcinoma (EC) that can affect any part of the esophagus, but is usually located in the upper or middle third. "Esophageal squamous cell carcinoma with high SAA1 expression were highly aggressive and closely associated with distant metastasis of esophageal squamous cell carcinoma." (PMID 37081987, 2023). "This study aimed to investigate the role of SAA1 in the progression of esophageal squamous cell carcinoma (ESCC) and its molecular mechanisms." (PMID 38446289, 2024).
hepatic disease (3 papers, 2021 to 2025). "In metabolic-associated steatotic liver disease models, deficiency of Saa1/Saa2 in mice due to genetic KO or shRNA knockdown ameliorates steatohepatitis, suggesting that SAA is pathogenic in high-fat diet–induced liver disease." (PMID 39969482, 2025). "Notably, the in vivo depletion of SAA1 in C57/BL6 mice significantly reduced the recruitment of HSCs and altered the expression of TLR2 at the site of injury, indicating that SAA1/TLR2 axis plays a critical role for inducing the recruitment of HSCs during hepatic disease response." (PMID 34113824, 2021).
influenza (3 papers, 2016 to 2026). An acute viral infection of the respiratory tract, occurring in isolated cases, in epidemics, or in pandemics; it is caused by serologically different strains of viruses (influenzaviruses) designated A, B, and C, has a 3-day incubation period, and usually lasts for 3 to 10 days. "The results showed that in influenza, high expression of SERPINA3, SAA1, and SAA2 was associated with a higher risk." (PMID 40158620, 2026). "In influenza, high expression of SERPINA3, SAA1, and SAA2 is associated with higher risk." (PMID 40158620, 2026).
injury (3 papers, 2020 to 2026). Damage inflicted on the body as the direct or indirect result of an external force, with or without disruption of structural continuity. "In summary, this work demonstrates that the SAA1/TLR2 axis is a critical mediator for migration of HSCs during acute liver injury." (PMID 34113824, 2021).
ischemic stroke (3 papers, 2015 to 2019). A stroke disorder caused by obstruction of blood flow to the brain, due to thrombotic (local blood clot formation) or embolic (due to a blood clot or other material traveling from another site) event. "Elevated CRP and SAA1, which we observed in the ischemic stroke subtype comparisons or in CBS deficiency, were also observed in Han Chinese ischemic stroke patients and in cardioembolic and large-vessel childhood arterial ischemic stroke." (PMID 31242583, 2019). "Finally, the SAA1/2 concentrations of 40 ischemic stroke patients were confirmed using ELISA kits." (PMID 28701906, 2017).
lung neoplasm (3 papers, 2018 to 2021). A benign or malignant, primary or metastatic neoplasm involving the lungs. "SAA1 has been used as a non-invasive biomarker for the prognosis of many cancers, including stomach, breast, liver and lung neoplasms." (PMID 29740512, 2018). "There was also a significant positive correlation between acute-phase protein concentrations, SAA1, and CRP in patients with all types of lung neoplasm except adenocarcinoma, with correlation coefficients of 0.44 in SqCC, 0.72 in other NSCLC, and 0.80 in other lung neoplasms." (PMID 34439874, 2021).
oral cancer (3 papers, 2022 to 2025). "Moreover, previous study showed that SAA1 promotes tumor metastasis by inducing epithelial-mesenchymal transition in oral cancer." (PMID 37081987, 2023). "In oral cancer, SAA1 promotes tumor metastasis by inducing EMT." (PMID 36605443, 2022).
prostate carcinoma (3 papers, 2017 to 2025). A carcinoma that arises from epithelial cells of the prostate gland. "Next, we observed a significant inverse correlation between Sun2 and SAA1 in prostate cancer tissues (P = 0.0019)." (PMID 29163775, 2017). "And we found that overexpression or knockdown of Sun2 decreased or increased SAA1 expression, respectively, in prostate cancer cells." (PMID 29163775, 2017). "In addition, SAA1 was highly overexpressed in prostate cancer tissues as compared with normal tissues (P < 0.05)." (PMID 29163775, 2017). "We observed significant a significant inverse correlation between Sun2 and SAA1 in prostate cancer." (PMID 29163775, 2017). "Additionally, we also showed that serum amyloid A1 (SAA1) play a vital role in FAO, ATP and cell growth promoted by Sun2 loss in prostate cancer." (PMID 29163775, 2017). "And FAO, ATP level and cell growth increasing in sh-Sun2-downexpressing prostate cancer cells could be reversed by SAA1 interference Serum amyloid A protein (SAA) is an apolipoprotein that can replace apolipoprotein A1 (apoA1) as the major apolipoprotein of high density lipoprotein (HDL)." (PMID 29163775, 2017).
psoriasis (3 papers, 2021 to 2024). An autoimmune condition characterized by red, well-delineated plaques with silvery scales that are usually on the extensor surfaces and scalp. "In our previous study, we demonstrated that SAA1 overexpression in TG mice led to spontaneous psoriasis, in which IL-17 plays a key role." (PMID 33781747, 2021).
sarcoidosis (3 papers, 2020 to 2025). Sarcoidosis is a multisystemic disorder of unknown cause characterized by the formation of immune granulomas in involved organs. "The SAA1 gene showed multiple hit and splice site mutations among 116 sporadic sarcoidosis patients." (PMID 35860586, 2022). "Interestingly, proteomic analysis revealed two highly expressed SAA1 isoforms in all of the sarcoidosis sera and in none of the sera from healthy controls." (PMID 33679725, 2020).
type 2 diabetes (3 papers, 2022 to 2025). "SAA1 has been reported to be involved in type 2 diabetes and NAFLD." (PMID 38533529, 2024).
ulcerative colitis (3 papers, 2016 to 2024). An inflammatory bowel disease involving the mucosal surface of the large intestine and rectum. "Four (80%) of the associated genes with these CpG sites have been linked to either ulcerative colitis (IL4R and SAA1) or CRC (LAT2 and SAA2)." (PMID 27006956, 2016). "SAA1 has been identified as a biomarker in ulcerative colitis and sepsis." (PMID 38297162, 2024).
acute kidney injury (2 papers, 2015 to 2025). Sudden and sustained deterioration of the kidney function characterized by decreased glomerular filtration rate, increased serum creatinine or oliguria. "Thus, in this model where the mechanism of renal failure is the destruction of normal renal architecture by cyst expansion, the provision of normal cells with wild type Pkhd1 may be more critical than the role of tubulogenic SAA1." (PMID 26136112, 2015).
acute myeloid leukaemia (2 papers, 2017 to 2025). "Therefore, the relevant up-regulation of SAA1 and down-regulation of plasminogen may be due to the direct effect of these disturbed signalling pathways, and can be used for the diagnosis of acute myeloid leukaemia in future." (PMID 29180721, 2017).
brucellosis (2 papers, 2013 to 2024). Brucellosis is a bacterial infection that spreads from animals to people via unpasteurized dairy products or by exposure to contaminated animal products or infected animals. "In this study, we found that in patients with chronic Brucellosis, the levels of SAA2 were elevated compared to SAA1, while the expression levels of SAA1 during the chronic phase were comparable to those of healthy individuals." (PMID 39872944, 2024). "Notably, P02741 (CRP) and P0DJI9 (SAA2) showed differential expression across all three groups, while P0DJI98 (SAA1) did not exhibit differential expression between the chronic Brucellosis group and the healthy controls." (PMID 39872944, 2024).
Cachexia (2 papers, 2020). Severe weight loss, wasting of muscle, loss of appetite, and general debility related to a chronic disease. "First, we assessed SAA1 mRNA in multiple tissues including liver, tumor, spleen, kidney, and lung to attempt to discern where SAA1 may be produced during LLC‐induced cachexia." (PMID 33063952, 2020).
chorioamnionitis (2 papers, 2020 to 2022). A morphologic finding indicating inflammation of the fetal sac membranes. "We also found that SAA1 levels were markedly increased in maternal circulation in preterm birth with chorioamnionitis when compared with gestational age-matched iatrogenic preterm birth." (PMID 35990700, 2022). "A dramatic increase in SAA1 abundance was observed in maternal blood in preterm birth with infectious histologic chorioamnionitis as compared with that of iatrogenic preterm birth group." (PMID 32582166, 2020). "Additionally, pronounced increases in SAA1 levels in the maternal blood in preterm deliveries with infectious histologic chorioamnionitis as revealed in this study as well as in previous studies lend further support for the participation of SAA1 in infection-induced inflammation in labor process." (PMID 32582166, 2020). "Moreover, significant increases in SAA1 abundance were observed in the placental tissue or in the maternal blood in spontaneous deliveries without infection at term and in preterm birth with histological chorioamnionitis." (PMID 32582166, 2020). "SAA1 in maternal blood was also significantly increased in infection-induced preterm birth compared with iatrogenic preterm birth without labor and histologic chorioamnionitis." (PMID 35990700, 2022).
Crohn disease (2 papers, 2010 to 2023). A gastrointestinal disorder characterized by chronic inflammation involving all layers of the intestinal wall, noncaseating granulomas affecting the intestinal wall and regional lymph nodes, and transmural fibrosis. "SAA1/2 expression was increased in colon samples obtained from Crohn's Disease patients compared to controls." (PMID 21067563, 2010). "In summary, the stricturing and penetrating Crohn’s disease phenotype is characterized by distinct proteomic signatures, evidenced by elevated serum levels of WDR31, LRG1, and SAA1." (PMID 38069288, 2023).